TMX4 (thioredoxin related transmembrane protein 4)
Synonyms: KIAA1162; TXNDC13; DJ971N18.2; PDIA14
Tractability: Antibody: UniProt predicts a signal peptide or a membrane-spanning region. PROTAC: ubiquitination databases record sites on it; its protein half-life has been measured.
Gene: Protein-coding gene on chromosome 20 (7,977,346 to 8,019,813, reverse strand). Ensembl gene ENSG00000125827.
Subcellular location: Nucleus inner membrane; Endoplasmic reticulum membrane
Subcellular location (Human Protein Atlas): Nuclear membrane
Gene Ontology:
Molecular function: disulfide oxidoreductase activity
Cellular component: endoplasmic reticulum; endoplasmic reticulum membrane; endomembrane system; nuclear inner membrane
Genetic constraint (gnomAD): Loss-of-function variants: 19 observed, 22.37 expected, observed/expected ratio (o/e) 0.85, 90% interval 0.59 to 1.25. The upper end of that interval is the gene's LOEUF score, 1.25, which puts it in group 5 of 6, group 1 being the genes least tolerant of losing a copy. Missense variants: 363 observed, 371.38 expected, observed/expected ratio (o/e) 0.98, 90% interval 0.9 to 1.07. Synonymous variants: 149 observed, 135.79 expected, observed/expected ratio (o/e) 1.1, 90% interval 0.96 to 1.26.
Homologues: Orthologues: macaque TMX4 (97% identical), chimpanzee TMX4 (96% identical), rabbit TMX4 (85% identical), pig TMX4 (82% identical), rat Tmx4 (82% identical), guinea pig TMX4 (80% identical), mouse Tmx4 (80% identical), dog TMX4 (79% identical), tropical clawed frog tmx4 (44% identical), zebrafish tmx4 (34% identical), Caenorhabditis elegans pdi-2 (14% identical), Drosophila melanogaster Pdi (14% identical), and 6 more. Paralogues in human: TMX1 (32% identical), TXNDC11 (20% identical), P4HB (17% identical), PDILT (15% identical), PDIA2 (15% identical), PDIA4 (14% identical), PDIA6 (12% identical), PDIA3 (12% identical), TXNDC5 (11% identical), PDIA5 (11% identical), TMX3 (10% identical), ERP44 (9% identical), and 1 more.
Diseases named in the same sentence as TMX4 in open-access papers:
TMX4 is named in the same sentence as 10 diseases in open-access papers, as found by Europe PMC text mining. Sharing a sentence is not in itself a finding about the gene and the disease. The quoted sentences say what the papers report.
CNS cancers (2 papers, 2020). "Unlike previous findings, within the CGGA LGGGBM cohort, TMX2 was up-regulated in gliomas with mutant IDH and the expression of TMX4 in the two groups was not statistically significant." (PMID 32023222, 2020).
lung carcinoma (1 paper, 2022). "As expected, addition of mutant circ-TMX4 in H1299 cells failed to increase significantly lung cancer cell invasion, suggesting that circ-TMX4 promoted lung cancer cell invasion via sponging and inhibition of miR-622." (PMID 35064116, 2022). "To further study the impact of ERβ-altered circ-TMX4 on lung cancer cell invasion, we found that circ-TMX4 is derived from exon 2, 3, 4, 5 of TMX4 gene, and has a length of 337 bp." (PMID 35064116, 2022). "The results from qRT–PCR assays indicated that circ-TMX4 was significantly elevated in fresh lung cancer tumor tissues (T) compared to the paratumor normal tissues (N) from 36 patients." (PMID 35064116, 2022). "To further dissect how the ERβ/circ-TMX4/miR-622 axis can enhance lung cancer cell invasion, we searched for metastasis genes that are linked to circ-TMX4 or miR-622 in the lung cancer cell databases (circBase, CircNet and OncoLnc)." (PMID 35064116, 2022). "In our study, the data showed the reverse function was partial, suggesting that sponging miR-622 is only one of the signaling pathway engaged by ERβ-circ-TMX4 for lung cancer progression, others mechanisms remain to be determined." (PMID 35064116, 2022). "Our study also proved that CXCR4 was an oncogene under the regulation of ERβ/circ-TMX4/miR-622 signaling to promote lung cancer progression, thus our work established the foundation to target this signaling for developing new drugs for the better treatment of lung cancer." (PMID 35064116, 2022). "We found that over expressing circ-TMX4 could block shERβ-suppressed cell invasion of lung cancer cell." (PMID 35064116, 2022). "Yet, only miR-622 inhibitor could promote lung cancer cell invasion, therefore we focused on the functional interaction between circ-TMX4 and miR-622." (PMID 35064116, 2022). "The results showed that the addition of ERβ could promote lung cancer metastasis, and shcirc-TMX4 could block ERβ mediated progression of lung cancer." (PMID 35064116, 2022). "The results from the rescue assay in H1299 cells revealed that the oecirc-TMX4-increased lung cancer cell invasion could be partially reversed via oemiR-622." (PMID 35064116, 2022). "Consistent with this, shcirc-TMX4 could also partly reverse ERβ mediated lung cancer cell invasion." (PMID 35064116, 2022). "We also collected the clinicopathological data of lung cancer patients who underwent surgery in our hospital in the past two years (2019-2020), and the analysis showed that tumor size, T grade, N grade and differentiation had significant correlations with circ-TMX4 and/or miR-622 expression." (PMID 35064116, 2022). "The results from the transwell assays with matrigel-coated filters revealed that only knocking down hsa_circ_0001130 (circ-TMX4), but not hsa_circ_0082894, could suppress lung cancer cell invasion." (PMID 35064116, 2022).
retinal degeneration (1 paper, 2025). Degeneration of the retina. "Moreover, TMX4 has been shown to interact with calnexin, a protein whose impairment leads to retinal degeneration." (PMID 40429992, 2025).
tumor (5 papers, 2022 to 2025). "Circ-TMX4 acts as a sponge for miR-622, resulting in upregulation of CXCR4, a key mediator of metastasis, thus establishing the ERβ1/circ-TMX4/miR-622/CXCR4 axis as a novel pathway linking ERβ1 to tumor aggressiveness and therapy response." (PMID 40710178, 2025). "There were significant differences in FAM81A, PCNT, and TMX4 expressions between tumor tissues and normal tissues in multiple types of cancer based on TCGA and GTEx." (PMID 40155922, 2025). "TMX4, ALPL, PTX3, BHLHE40, TNFRSF12A and CST3 demonstrated significant overexpression in LUSC tumour tissues, whereas CLDN1, VKORC1 and ADD3 exhibited significant underexpression in the HPA database." (PMID 38520221, 2024). "Notably, TMX4, ALPL, PTX3, BHLHE40, TNFRSF12A and CST3 demonstrated significant overexpression in LUSC tumour tissues, whereas CLDN1, VKORC1 and ADD3 exhibited significant underexpression." (PMID 38520221, 2024). "Furthermore, ERβ1 facilitates tumor invasion through a non-genomic mechanism by transcriptionally activating thioredoxin-related transmembrane protein 4 (TMX4), which elevates circ-TMX4 levels." (PMID 40710178, 2025).
cancer (2 papers, 2023 to 2025). A tumor composed of atypical neoplastic, often pleomorphic cells that invade other tissues. "In this study, based on TCGA and GTEx databases, we analyzed the expression of TMX family (TMX1, TMX2, TMX3, and TMX4) genes in 23 different cancer types." (PMID 38147024, 2023). "By estimating StromalScore and ImmuneScore in TME, we found that TMX1, TMX3, and TMX4 exhibited a positive correlation with StromalScore and StromalScore in most cancer types, while TMX2 expression was negatively correlated with StromalScore and ImmuneScore." (PMID 38147024, 2023). "TMX4 was significantly down-regulated in 6 cancer types and up-regulated in 4 cancer types." (PMID 38147024, 2023). "Furthermore, we also investigated the correlation of TMX2 and TMX4 expression with immune-checkpoint-related stimulator genes in pan-cancer." (PMID 38147024, 2023). "To gain a better understanding of the biological mechanism of TMX family genes in cancers, we conducted KEGG signaling pathway enrichment analysis on TMX family genes (TMX2 and TMX4) with different expression phenotypes in KIRC and LIHC, respectively." (PMID 38147024, 2023).
TMX4 also shares sentences with these, for which no sentence is quoted: glioma (2 papers); brain cancer (1); liver cancer (1); nicotine dependence (1); non-small cell lung carcinoma (1).